GOLGA1 (golgin A1)
Description:
Involved in vesicular trafficking at the Golgi apparatus level. Involved in endosome-to-Golgi trafficking. Mechanistically, captures transport vesicles arriving from endosomes via the protein TBC1D23. Recognized vesicles are then tethered to the trans-Golgi before subsequent SNARE engagement and vesicle fusion. Selectively regulates E-cadherin transport from the trans-Golgi network in tubulovesicular carriers. (Microbial infection) Plays an important role in poxvirus morphogenesis. Translocates into the viral factories where it may transport the membrane fragments and associated protein factors important for virus maturation to the sites of virion assembly.
Synonyms: golgin-97; MGC33154
Tractability: Antibody: UniProt places it where antibodies can reach, with high confidence. PROTAC: ubiquitination databases record sites on it; its protein half-life has been measured.
Gene: Protein-coding gene on chromosome 9 (124,878,275 to 124,948,492, reverse strand). Ensembl gene ENSG00000136935.
Subcellular location: Golgi apparatus membrane; Golgi apparatus, trans-Golgi network membrane; Cytoplasmic vesicle, secretory vesicle, acrosome
Subcellular location (Human Protein Atlas): Golgi apparatus
Pathways (Reactome):
Vesicle-mediated transport: Retrograde transport at the Trans-Golgi-Network
Gene Ontology:
Molecular function: molecular carrier activity; protein binding
Biological process: transepithelial transport
Cellular component: Golgi apparatus; Golgi membrane; trans-Golgi network; cytosol; acrosomal vesicle; perinuclear region of cytoplasm
Genetic constraint (gnomAD): Loss-of-function variants: 25 observed, 50.86 expected, observed/expected ratio (o/e) 0.49, 90% interval 0.36 to 0.69. The upper end of that interval is the gene's LOEUF score, 0.69, which puts it in group 2 of 6, group 1 being the genes least tolerant of losing a copy. Missense variants: 411 observed, 458.28 expected, observed/expected ratio (o/e) 0.9, 90% interval 0.83 to 0.97. Synonymous variants: 154 observed, 171.46 expected, observed/expected ratio (o/e) 0.9, 90% interval 0.79 to 1.03.
Homologues: Orthologues: chimpanzee GOLGA1 (99% identical), macaque GOLGA1 (97% identical), pig GOLGA1 (86% identical), dog GOLGA1 (84% identical), guinea pig GOLGA1 (83% identical), rabbit GOLGA1 (83% identical), mouse Golga1 (81% identical), rat Golga1 (80% identical), tropical clawed frog golga1 (55% identical), zebrafish golga1 (51% identical), Drosophila melanogaster Golgin97 (22% identical). Paralogues in human: GCC1 (18% identical).
Diseases named in the same sentence as GOLGA1 in open-access papers:
GOLGA1 is named in the same sentence as 18 diseases in open-access papers, as found by Europe PMC text mining. Sharing a sentence is not in itself a finding about the gene and the disease. The quoted sentences say what the papers report.
breast carcinoma (4 papers, 2018 to 2023). "GOLGA1 plays a role in trafficking proteins through the Golgi apparatus, with poor patient survival rates and increased invasiveness rates seen in breast cancer patients who use this protein." (PMID 37508488, 2023).
colon cancer (2 papers, 2023). "Other Golgi proteins such as GOLGA1 (golgin-97) and GOLGA7 (golgin-84) have been implicated in colon cancer." (PMID 37508488, 2023).
gastric cancer (1 paper, 2023). A primary or metastatic malignant neoplasm involving the stomach. "Gastric cancer involves numerous Golgi proteins such as GM130 (GOLGA2), GOLPH3, golgin-160 (GOLGA4), golgin-97 (GOLGA1) and golgin-84 (GOLGA7) that all play unique roles in cell processes including protein glycosylation, vesicle trafficking and Golgi structure maintenance." (PMID 37508488, 2023).
lymph node metastasis (1 paper, 2022). "A similar well-designed study aimed at identifying the genes associated with the involvement of lymph node metastasis in patients with PCa and, among 376 genes investigated, three genes, RALGPS1, ZBTB34 and GOLGA1, had a significant copy number alteration." (PMID 36077746, 2022).
Sjögren’s syndrome (1 paper, 2021). "GOLGA1 (Golgin-97): This protein was identified as an autoantigen in patients with Sjögren’s syndrome." (PMID 34943782, 2021).
tumor (4 papers, 2017 to 2025). "GOLGA7B and GOLGA1 were identified as novel genes associated with the tumor grade of ESCC." (PMID 28904855, 2017).
GOLGA1 also shares sentences with these, for which no sentence is quoted: cancer (4 papers); infection (2); ductal breast carcinoma (1); ductal breast carcinoma in situ (1); glioma (1); invasive ductal breast carcinoma (1); large cell lung carcinoma (1); leukemia (1); mastocytoma (1); Parkinsonism (1); schizophrenia (1); small cell lung carcinoma (1).